RNU6-1096P (RNA, U6 small nuclear 1096, pseudogene)
Gene: Small nuclear RNA gene on chromosome 4 (173,446,603 to 173,446,704, reverse strand). Ensembl gene ENSG00000252898.
Homologues: Orthologues: chimpanzee U6 (99% identical), macaque U6 (95% identical), guinea pig U6 (71% identical), dog U6 (68% identical), rat LOC120098446 (65% identical), mouse Gm26038 (63% identical). Paralogues in human: RNU6-140P (85% identical), RNU6-206P (84% identical), RNU6-480P (84% identical), RNU6-698P (84% identical), RNU6-1038P (83% identical), RNU6-116P (83% identical), RNU6-664P (83% identical), RNU6-1026P (82% identical), RNU6-1031P (82% identical), RNU6-144P (82% identical), RNU6-16P (82% identical), RNU6-25P (82% identical), and 1287 more.